LINC00370 (long independently transcribed non-coding RNA 370)
Synonyms: AL161431.1; RP11-54H7.4; LINC03061; LOC130494219
Gene: Long non-coding RNA gene on chromosome 13 (109,265,416 to 109,307,831, forward strand). Ensembl gene ENSG00000223617.
Diseases named in the same sentence as LINC00370 in open-access papers:
LINC00370 is named in the same sentence as 5 diseases in open-access papers, as found by Europe PMC text mining. Sharing a sentence is not in itself a finding about the gene and the disease.
LINC00370 shares sentences with these, for which no sentence is quoted: pancreatic cancer (3 papers); cancer (2); endometrial carcinoma (2); tumor (2); lung carcinoma (1).